IL6 (interleukin 6)
Diseases named in the same sentence as IL6 in open-access papers (continued):
Sharing a sentence is not in itself a finding about the gene and the disease.
cancer (continued). "The results showed that compared with the control, ART1-sh cancer cells induced by IL-6 exhibited reduced viability, a lower rate of colony formation, less DNA synthesis, decreased protein levels of gp130, c-Myc, cyclin D1, Bcl-xL, and a reduced p-STAT3/STAT3 ratio (P < 0.05)." (PMID 38504172, 2024). "However, few studies on blockade of IL-6 trans-signaling in cancer patients have been reported, despite its therapeutic effects in numerous preclinical cancer models." (PMID 38182653, 2024). "The strong binding affinity indicated by the hydrogen bonds implies that RIPs could play a pivotal role in insilico drug design targeting IL-6, potentially opening up novel avenues in cancer treatment." (PMID 38801471, 2024). "IL-6-inducing activity, which was also found in urine from cancer patients, could be adsorbed by PBMCs." (PMID 39518029, 2024). "IL6, an oncogenic cytokine, was notably down‐regulated in 10 cancers." (PMID 38627900, 2024). "Enhanced levels of many cytokines related to cancer invasion and migration are found in the CMs of ET-1-treated cells, including IL-6, IL-8, CXCL11, and CXCL12, further supporting the hypothesis that ET-1 is a driver of activated fibroblasts." (PMID 38777849, 2024). "To illustrate, administering drugs to cancer patients that focus only on inhibiting IL‐6 could be more effective when TNF‐α is low (group 3) than when it is high (groups 2 and 4)." (PMID 38481033, 2024). "The IL-6 binds to IL-6R on the receptor of cancer cells to induce STAT3 axis." (PMID 39014491, 2024). "After exposure to multiple inflammatory microenvironmental factors, molecules such as IL-4, IL-6, IL-8, IL-17α, IL-22, IL-23, IL-33, and interferon-γ, induce complex genetic/molecular changes in precancerous stem cells (pCSC) to gradually form cancer stem cells (CSCs)." (PMID 39073546, 2024). "In ovarian cancer, polyploid giant cancer cells are induced by senescence-related IL-6 and activate the embryonic dedifferentiation program during the initial stage of formation while stimulating normal fibroblasts to reprogram into cancer-related fibroblasts (CAFs)." (PMID 38540708, 2024). "According to the literature, a significant increase in the levels of pro-inflammatory mediators, primarily pro-inflammatory cytokines like interleukin (IL)-6 and tumor necrosis factor (TNF), is closely associated with increased proliferation and enhanced survival of cancer cells." (PMID 38337668, 2024). "In Cluster 3, research could focus on how stress and psychological factors affect salivary biomarkers in cancer survivors and the role of cytokines such as interleukin-6 and interleukin-10 in mental health." (PMID 39021745, 2024). "In vitro experiments further demonstrated that recombinant IL-6 at concentrations of 10 and 100 pg/mL could inhibit human CRC cell proliferation and reduce γ-H2AX expression, reflecting the anti-cancer properties associated with exercise." (PMID 39346906, 2024). "IL-6 can promote malignant cell proliferation, angiogenesis, and metastasis in other cancers." (PMID 38649788, 2024). "Interleukin-6 is an essential element in the cancer microenvironment and may be generated by both cancer cells and their associated stromal equivalents, such as CAFs." (PMID 38519574, 2024). "Furthermore, mesothelin promotes cancer cell survival and proliferation through the activation of cyclin E and IL-6 signaling pathways." (PMID 38396817, 2024). "To confirm whether IL-6 is mainly secreted by the CAFs, we initially detected the mRNA level of IL-6 in both CAFs and cancer cells." (PMID 38459511, 2024). "The role of Il-10 in cancer pathogenesis and development is complex; Il-10 also plays an important role as an anti-inflammatory marker, inhibiting the synthesis of proinflammatory cytokines such as Il-6." (PMID 39202525, 2024). "Blocking the receptors for IL-6 results in anti-proliferative effects on cancer cells." (PMID 39206193, 2024).
cancer (continued). "Future studies should focus on elucidating the specific molecular pathways involved in ASC-mediated chemoresistance and exploring potential strategies to overcome this resistance, such as targeting IL-6 signaling or other key mediators of the ASC–cancer cell interaction." (PMID 39766174, 2024). "The resulting immunosensors could also be versatile tools to detect IL6 and other biomarkers related to the diagnosis/prognosis of immune-mediated diseases and cancer." (PMID 39432122, 2024). "Co-culturing of adipocytes and cancer cells leads to the upregulation of many pro-inflammatory cytokines such as family members of interleukin-6 (IL-6), a multifunctional cytokine in host defense, and CXCL1, which is a chemoattractant for many immune cells, including neutrophils." (PMID 39596205, 2024). "Moreover, IL-6 induces the passage of stem cells from the G0 phase of the cell cycle to Phase G1, thereby maintaining the cancer stem cell population." (PMID 39201656, 2024). "Our preclinical studies suggested that systematically targeting the MCT-1/IL-6/IL-6R/CXCL7/PD-L1 nexus could be a new medical opportunity that would benefit long-term cancer control and disease-free survival." (PMID 38505617, 2024). "A master player in the E2F1-induced cancer-immune cell crosstalk is IL-6." (PMID 39544930, 2024). "An increased level of sleep-mediating cytokines, such as IL-6, TNF-α, and sTNF-R in cancer patients could cause impaired sleep quality." (PMID 38257176, 2024). "Functional analysis further revealed that KRAS mutations led to upregulation of WNT, MAPK, and IL-6/JAK/STAT signaling pathways, which are known to facilitate cancer cell proliferation, growth, and invasion, resulting in more aggressive disease and reduced treatment response." (PMID 38783092, 2024). "IL-6 and related cytokines are critical in the interplay between inflammation and cancer." (PMID 39421736, 2024). "Physiological dysregulation of cytokines, such as tumor necrosis factor-alpha and interleukin 6, in patients with tumors may impede albumin synthesis by hepatocytes, influencing cancer progression and neoangiogenesis." (PMID 39624689, 2024). "Co-transfection of cancer cells with IL-6 3′UTR reporter clone + anti-miR-26a-5p significantly increased relative luciferase activity in a dose-dependent manner of anti-miR-26a-5p, compared to the cancer cells transfected with the IL-6 3′UTR reporter clone alone." (PMID 38338683, 2024). "Combining checkpoint inhibitor therapy with drugs targeting specific pathways of IL6 might enhance efficacy, improve survival, and overcome cancer resistance." (PMID 39766086, 2024). "Meanwhile, in the context of drug resistance, it is approved that CAFs activate the JAK-STAT3 and PI3K-Akt pathways in cancer cells by secreting IL-6, inducing the up-regulation of epithelial − mesenchymal transition (EMT) and E3 ubiquitin ligase complex function." (PMID 39030445, 2024). "This is attributed to the impairment of T-cell activation and the subsequent stimulation of the production of transforming growth factor β (TGF-β1), prostaglandin E2 (PGE2), transforming growth factor-α (TNF-α), and interleukin-6 (IL-6), which are pivotal in the pathogenesis of both cancer and OSF." (PMID 39682896, 2024). "Among these, IL-6 plays a central role in human cancer progression." (PMID 38671854, 2024). "Drugs targeting IL-6 are gradually being used in the clinic to treat cancer." (PMID 38424624, 2024). "Sera from cancer patients with a high IL-6 production in autologous cultures induced IL-6 in cultures with normal PBMCs in five out of five cultures (patients 1–5) demonstrating the presence of an IL-6-inducing serum factor." (PMID 39518029, 2024). "IL6 inhibitors have been shown to prevent the conversion of non-stem cancer cells to cancer stem cells and alleviate cancer-associated anemia by increasing hemoglobin and reducing CRP levels." (PMID 39766086, 2024).
cancer (continued). "In conclusion, for patients with NSCLC accompanied by cachexia and elevated plasma IL‐6 levels, the addition of tocilizumab to standard anticancer treatments appears to mitigate the effects of cancer cachexia and extend survival, while also enhancing tolerance to conventional oncologic therapies." (PMID 39523982, 2024). "Thus, it is possible that IL-6 fuels cancer cell dissemination from primary sites and colonization to distant organs, which requires further investigation." (PMID 38459511, 2024). "IL-6 has long been known as a key contributor to cancer cachexia." (PMID 38824130, 2024). "IL-6 production induced by IL-6IF and cancer patient sera is inhibited by specific antibodies." (PMID 39518029, 2024). "IL-6, a marker of chronic inflammation, is well-studied in cancer." (PMID 39355131, 2024). "IL-6 is a key immunomodulatory cytokine, which is involved in the orchestration of the innate and acquired immune system and plays an important role in the regulation of various homeostatic to pathological processes such as immune disease and cancers." (PMID 38398148, 2024). "For example, while median IL6 serum level in control cohorts was 1.31 pg/mL (range 0–37 pg/mL), the overall median of the reported cut-offs of serum IL6 was 10 pg/mL (range: 1.9–130 pg/mL) in cancer patients." (PMID 39432122, 2024). "However, no significant decrease in serum IL-6 was observed, indicating that ASH extract had few effects on IL-6 production in cancer." (PMID 39281184, 2024). "Notably, IL6 emerged as the gene with the highest upregulation, demonstrating a remarkable 103-fold increase in this group of cancers compared to the rest of the cancer samples." (PMID 38979413, 2024). "Cancer cells after immortalized PDT significantly upregulated a number of immune-related genes, including chemokine genes (CXCL2, CXCL3, IL8/CXCL8) as well as genes encoding interleukin-6 (IL-6) and its receptor (IL6R)." (PMID 38397977, 2024). "Interestingly, our study noted that both IL6 and TNFα levels were significantly higher in the control population compared to the cancer population, although the significance was lost when the adjusted p-value was used for TNFα." (PMID 38339282, 2024). "Furthermore, the administration of anti-IL-6 monoclonal antibody in mice was found to partially inhibit the progression of cancer cachexia." (PMID 38828409, 2024). "Moreover, in the established highly metastatic cells, EMT induction was enhanced compared to that in the parent cell line, and CCL5 and IL-6 secreted during inflammation further enhanced EMT induction in cancer cells." (PMID 39126553, 2024). "High neutrophil levels in tissues secrete numerous inflammatory mediators like vascular endothelial growth factor (VEGF), tumor necrosis factor-a (TNF-a), interleukin-2 (IL-2), interleukin-10 (IL-10), and interleukin-6 (IL-6) which creates a suitable environment for cancer progression." (PMID 38166889, 2024). "Furthermore, CSC-Exos expressing IL-6, p-STAT3, TGF-β1, and β-catenin promote the generation of cancer-associated fibroblasts and M2 macrophages in colon cancer." (PMID 39200273, 2024). "The evidence of elevated IL6 expression in our study might shed light on the mechanism of higher incidence of cancers reported in animals and humans exposed to both AFB1 and FB1." (PMID 38468450, 2024). "Pro-inflammatory cytokines such as TNF alpha, IL-6, and IL-1beta and transcription factors like NF-kappaB and STATs are increased in chronic inflammation and play a huge role in this process, leading to cancer development." (PMID 38792785, 2024). "Interleukin-6 (IL-6) has been long considered a key player in cancer cachexia." (PMID 38824130, 2024).
cancer (continued). "Supporting this idea, it has been demonstrated that IL-6 levels may predict immunotherapy response in other carcinomas." (PMID 38672565, 2024). "IL-6 secreted from cancer cells has been shown to induce lipolysis." (PMID 37998333, 2023). "In addition, IL-8 is one of the most significant activating chemokine of cancer-associated cells, along with TNF-α and IL-6, which contribute to the proinflammatory profile of the TME in CRC patients." (PMID 37760840, 2023). "In particular, the IL-6- JAK-STAT3 signaling pathways plays a crucial role in human cancer." (PMID 36917087, 2023). "RP treatment suppressed serum TNF-α and IL-6, elevated by cancer allograft." (PMID 37240117, 2023). "IL-6 and Activin A have a synergic role in inducing Noggin overexpression that causes NMJ impairment and atrophy, whereas treatment aimed to increase BMP signaling attenuate muscle atrophy during cancer cachexia." (PMID 38203683, 2023). "The results showed that levels of IL-6, IL-8 and IL-10 in serum were higher in malignant tumor group than that in benign tumor and control group; the expression levels of IL-6 and IL-8 were significantly elevated in grade III than in grade I and II and was related to metastasis." (PMID 36693957, 2023). "Interleukin‐6 (Il‐6) was deleted from cancer cells using CRISPR/Cas9 mediated gene editing." (PMID 36351437, 2023). "These, in turn, can reactivate dormant DTC proliferation, renew CD133+ cancer cells and endocrine resistance by IL-6/Notch signaling through the IL-6 receptor gp130/gp80 and activated STAT3, through VEGF via PI3K/Akt signaling, SMAD2 and 3, and the EGFR and ERK pathways." (PMID 37296983, 2023). "Thus, based on both clinical and experimental evidence, agents targeting IL-6 signaling are plausible partners for combination with ICIs in cancer patients." (PMID 36599350, 2023). "The inflammatory markers interleukin 6 (IL‐6) and tumor necrosis factor alpha (TNFα) were included as inflammation may play a role in cancer recurrence and mortality." (PMID 37269192, 2023). "Inflammatory markers and fatigue are closely related during the treatment of cancer patients, with high levels of interleukin 6 (IL-6), interleukin 1 (IL-1), and tumor necrosis factor-alpha positively correlating with the degree of fatigue after chemotherapy in cancer patients." (PMID 37542585, 2023). "We hypothesized that IL-6 secreted by genotoxic treatments of cancer cells plays a key role in driving M2 macrophage polarization." (PMID 37696858, 2023). "Interleukin-6 (IL-6) as a multifactorial cytokine may have a role in the severity and progression of numerous types of cancers." (PMID 38024543, 2023). "Our data demonstrate that genotoxic-induced IL-6-mediated M2-like macrophage polarization not only dampens their anti-survival activities but also augments their pro-migratory and -invasive effects on cancer cells." (PMID 37696858, 2023). "Cancer-promoting cytokines like IL-6, IL-11, TNF-α, IL-1β, and IL-23 vary by tumor type and stage." (PMID 37229273, 2023). "Further, to investigate whether the cancer stem cell expansion triggered by IL-6 and IL-8 was dependent on sortilin, the small sortilin-binding molecule AF38469 was used." (PMID 38136303, 2023). "This overexpression of IL-6 plays a major role in inflammatory diseases and cancer." (PMID 37588093, 2023). "Furthermore, the pro-inflammatory factors secreted by cancer cells, such as IL-6 and CXCL10, can upregulate the expression of LINC01614 through a feedforward loop." (PMID 37784082, 2023). "IL-6 is released by various cells including cancer cells, CAFs, and immune cells." (PMID 37480115, 2023). "Similar results of IL-6 induced by YAP were shown in cancer cells, while other studies reported that suppression of YAP might prolong and worsen the inflammation in lung tissue." (PMID 37877098, 2023).
cancer (continued). "However, among BC patients, taking into account the stage of cancer, we confirmed that the lowest degree of methylation was found in patients from the T1 subgroup, which corresponded to the highest level of IL-6 expression." (PMID 37047238, 2023). "TANs provide a favorable environment for cancer development, angiogenesis and metastatic spread by secreting cytokines and chemokines, such as interleukin-2 (IL-2), interleukin-6 (IL-6), interleukin-10 (IL-10), tumor necrosis factor α (TNF-α) and vascular endothelial growth factor (VEGF)." (PMID 36661728, 2023). "In addition, IL-6 regulates cancer stem cells, mesenchymal stem cell formation, and epithelial to mesenchymal transition in cancer and contributes to chemoresistance." (PMID 37204272, 2023). "Blockade of the IL-6 signalling pathway has become a target for the therapy of diverse cancers." (PMID 37215450, 2023). "Cancer-associated fibroblasts activate fibroblasts that reside in the TME and produce a large number of chemokines, growth factors like TGF-β, cytokines like IL-1β, IL-6, IL-8, and collagen." (PMID 37514090, 2023). "In NSCLC, epigenetic modification of IL-1β, IL-8, and IL-6 expressions could affect inflammatory response during cancer development." (PMID 36986550, 2023). "Dysregulated miR-197 in various cancers received sophisticated regulatory: IL-6 appeared to stimulate and increase the levels of p-SATA3 and STAT3 protein, which inhibited the expression of miR-197 and thus contributed to oncogenesis via promoting cell proliferation, preventing apoptosis." (PMID 35913675, 2023). "The IL-6/JAK/STAT signaling pathway is aberrantly hyperactivated in many types of cancer." (PMID 37215450, 2023). "In this study, we examined whether SC-1 inhibits TGFβ-mediated IL-6 and IL-8 expressions in cancer cell lines." (PMID 37511415, 2023). "IL-6 is a pivotal cytokine in many cancer settings, including CRC." (PMID 37460938, 2023). "Moreover, in murine xenograft models, IL-6 and IL-8 production by OS cells correlated with cancer cell metastatic potential." (PMID 37760046, 2023). "On the one hand, IL-6 displays antitumorigenic effects on cancer cells." (PMID 36794014, 2023). "These proinflammatory cytokines are generally responsible for immune response activation (i.e., IL-6), cytotoxic and cytostatic effects against cancer cells (i.e., TNF-α), and the recruitment and activation of immune cells along with other pro-inflammatory cytokines (i.e., IL-1β)." (PMID 37760610, 2023). "Serum IL-6 level increased by cancer cells was reduced by CR administration." (PMID 37240117, 2023). "Preclinical studies of IL-6/IL-6R blockade to target MDSCs in cancer have been conducted." (PMID 37006306, 2023). "Moreover, IL-6 can function as a growth factor, and it promotes cancer progression by regulating multiple signaling pathways." (PMID 37189804, 2023). "Also, we found that the serum IL-6 level decreased significantly in capsaicin-induced systemic inflammation, contrary to previous reports that cancer-related chronic inflammation is accompanied by an increase in IL-6." (PMID 36904069, 2023). "Cancer cells treated with EFGR-tyrosine kinase inhibitor show an increased expression of IL-6 mRNA." (PMID 37119853, 2023). "Therefore, the aim of this meta-analysis was to clarify the correlations of the IL-10 rs1800896 and rs1800872 and IL-6 rs1800795 gene polymorphisms with the SCC risk, including subgroup analyses by ethnicity, control source, and cancer type." (PMID 37077342, 2023). "Interleukin-6 (IL-6) is a critical cytokine and key inflammatory mediator within the TME that is strongly implicated in almost all hallmarks of cancer such as inflammation, cell proliferation/inhibition of cell death, migration/invasiveness, and metastasis formation." (PMID 37173331, 2023).